PRDX4 (peroxiredoxin 4)
Diseases named in the same sentence as PRDX4 in open-access papers (continued):
Sharing a sentence is not in itself a finding about the gene and the disease.
PRDX4 also shares sentences with these, for which no sentence is quoted: Hypertension (4 papers); polycystic ovary syndrome (4); bacterial infection (3); Insulin resistance (3); leukemia (3); Nonalcoholic Fatty Liver Disease (3); chronic kidney disease (2); colon (2); colon adenocarcinoma (2); malignant melanomas (2); pancreatic cancer (2); age (1); aortic stenosis (1); Astrocytoma (1); autoimmune bullous skin disease (1); autoimmune disease (1); bone metastasis (1); cerebrovascular disease (1); cervical cancer (1); colorectal (1); colorectal tumors (1); COVID-19 (1); demyelinating disease (1); depression (1); diabetic cardiomyopathy (1); diabetic retinopathy (1); dyslexia (1); esophageal cancer (1); experimental autoimmune encephalomyelitis (1); Fanconi anaemia (1).
A further 31 diseases each share a sentence with PRDX4 in 1 paper.